ANKRD13C-DT (ANKRD13C divergent transcript)
Synonyms: HHLA3
Gene: Long non-coding RNA gene on chromosome 1 (70,354,780 to 70,385,339, forward strand). Ensembl gene ENSG00000197568.
Diseases named in the same sentence as ANKRD13C-DT in open-access papers:
ANKRD13C-DT is named in the same sentence as 2 diseases in open-access papers, as found by Europe PMC text mining. Sharing a sentence is not in itself a finding about the gene and the disease.
ANKRD13C-DT shares sentences with these, for which no sentence is quoted: clear cell renal cell carcinoma (1 paper); diabetes (1).